ZNF263 (zinc finger protein 263)
Description:
Transcription factor that binds to the consensus sequence 5'-TCCTCCC-3' and acts as a transcriptional repressor. Binds to the promoter region of SIX3 and recruits other proteins involved in chromatin modification and transcriptional corepression, resulting in methylation of the promoter and transcriptional repression. Acts as a transcriptional repressor of HS3ST1 and HS3ST3A1 via binding to gene promoter regions.
Synonyms: FPM315; ZKSCAN12; ZSCAN44
Tractability: PROTAC: UniProt records ubiquitination sites on it; ubiquitination databases record sites on it.
Gene: Protein-coding gene on chromosome 16 (3,263,800 to 3,301,401, forward strand). Ensembl gene ENSG00000006194.
Subcellular location: Nucleus
Subcellular location (Human Protein Atlas): Cytosol; Mitotic spindle; Nucleoplasm
Pathways (Reactome):
Gene expression (Transcription): Generic Transcription Pathway
Gene Ontology:
Molecular function: DNA-binding transcription repressor activity, RNA polymerase II-specific; protein binding; sequence-specific DNA binding; sequence-specific double-stranded DNA binding; transcription cis-regulatory region binding; DNA-binding transcription factor activity; DNA-binding transcription factor activity, RNA polymerase II-specific; RNA polymerase II cis-regulatory region sequence-specific DNA binding
Biological process: negative regulation of transcription by RNA polymerase II; positive regulation of transcription by RNA polymerase II; regulation of DNA-templated transcription; regulation of transcription by RNA polymerase II
Cellular component: cytosol; nucleus
Genetic constraint (gnomAD): Loss-of-function variants: 49 observed, 63.06 expected, observed/expected ratio (o/e) 0.78, 90% interval 0.62 to 0.99. The upper end of that interval is the gene's LOEUF score, 0.99, which puts it in group 4 of 6, group 1 being the genes least tolerant of losing a copy. Missense variants: 864 observed, 886.01 expected, observed/expected ratio (o/e) 0.98, 90% interval 0.92 to 1.03. Synonymous variants: 352 observed, 336.38 expected, observed/expected ratio (o/e) 1.05, 90% interval 0.96 to 1.14.
Homologues: Orthologues: chimpanzee ZNF263 (99% identical), macaque ZNF263 (99% identical), dog ZNF263 (92% identical), pig ZNF263 (89% identical), rabbit ZNF263 (87% identical), guinea pig ZNF263 (86% identical), mouse Zfp263 (84% identical), rat Zfp263 (83% identical). Paralogues in human: ZKSCAN8 (30% identical), ZSCAN25 (30% identical), ZNF397 (29% identical), ZSCAN22 (29% identical), ZKSCAN1 (28% identical), ZNF394 (28% identical), ZKSCAN4 (28% identical), ZKSCAN3 (28% identical), ZSCAN12 (28% identical), ZSCAN30 (28% identical), ZSCAN21 (27% identical), ZSCAN26 (27% identical), and 18 more.
Diseases named in the same sentence as ZNF263 in open-access papers:
ZNF263 is named in the same sentence as 20 diseases in open-access papers, as found by Europe PMC text mining. Sharing a sentence is not in itself a finding about the gene and the disease. The quoted sentences say what the papers report.
hepatocellular carcinoma (2 papers, 2022 to 2025). A malignant tumor that arises from hepatocytes. "According to reports, ZNF263 is a key transcription factor for cholangiocarcinoma, gastric cancer, and hepatocellular carcinoma." (PMID 35494064, 2022). "Moreover, O-GlcNAc of ZNF263 at Ser 662 promotes its chromatin association with OGT and facilitates its binding to the promoters of genes such as DOCK7, NPTX1, and UFSP2, thereby influencing hepatocellular carcinoma (HCC) progression." (PMID 41280891, 2025).
renal cell carcinoma (2 papers, 2021 to 2024). "For instance, research has demonstrated that ZNF263 interacts with two splice sites (P3 and P4) on the FOXP1 promoter, thereby regulating the expression of circFOXP1 in renal cell carcinoma (RCC) cells, which promotes RCC cell proliferation, migration, invasion, and the Warburg effect." (PMID 39606233, 2024).
colorectal cancer (1 paper, 2025). A primary or metastatic malignant neoplasm that affects the colon or rectum. "Research has shown that the overexpression of zinc finger protein 263 (ZNF263) markedly promotes the proliferation, invasion, migration, and EMT of colorectal cancer (CRC) cells, concomitantly elevating STAT3 expression and mRNA stability." (PMID 40772037, 2025).
glioblastoma (1 paper, 2020). The most malignant astrocytic tumor (WHO grade IV). "Here, we firstly showed that EGFR/MAPK hyperactivation results in epigenetic silencing of SIX3 through ZNF263 in glioblastoma." (PMID 32051553, 2020). "We expressed EGFR-vIII in glioblastoma cells, which expectedly increased ZNF263 levels and decreased SIX3 levels." (PMID 32051553, 2020). "Thus, both p-EGFR and ZNF263 can be used as an indicator for poor prognosis while SIX3 serves as an indicator for favorable prognosis of glioblastoma." (PMID 32051553, 2020). "Thus, ERK1/2 interacts directly with ZNF263 through the ERK D-domain, and the interaction is vital for maintaining the stability of ZNF263 in glioblastoma cells." (PMID 32051553, 2020). "To investigate the function of ZNF263 and SIX3 in the context of glioblastoma development, we first treated the phenotypically normal astrocytes (HEB cells) with high doses of EGF to mimic EGFR/MAPK hyperactivation during tumor initiation." (PMID 32051553, 2020). "Overexpression of ZNF263 in glioblastoma cells decreased the expression of SIX3, while ZNF263 depletion markedly elevated SIX3 level." (PMID 32051553, 2020). "In contrast, ZNF263 knockdown, Trametinib treatment, or ectopic expression of SIX3 prevented the tumor-promoting effects of EGFR-vIII on glioblastoma cells." (PMID 32051553, 2020). "Because ZNF263 plays a critical role in epigenetic silencing of SIX3 in glioblastoma, we next examined whether erlotinib or Trametinib induced SIX3 expression through the regulation of ZNF263." (PMID 32051553, 2020). "We found that erlortinib did not decrease and instead slightly elevated mRNA levels of ZNF263 in glioblastoma cells." (PMID 32051553, 2020). "The effects of ZNF263 on H3K27me3 and H3K9me3 led us to ask whether ZNF263 alter chromatin accessibility of SIX3 promoter in glioblastoma." (PMID 32051553, 2020). "We first treated glioblastoma cells with cycloheximide to block de novo protein synthesis and then added Trametinib to inhibit the MAPK pathway, which resulted in a dramatic decrease in the half-life of ZNF263." (PMID 32051553, 2020). "Intriguingly, Trametinib appeared to specifically reduce ZNF263 protein levels without altering those of KAP1, SUV39H2, EED, or SETDB1, implying that the activation of EGFR/MAPK led to SIX3 silencing in glioblastoma mainly through the regulation of ZNF263." (PMID 32051553, 2020).
glioma (1 paper, 2020). A benign or malignant brain and spinal cord tumor that arises from glial cells (astrocytes, oligodendrocytes, ependymal cells). "We first assessed the expression of ZNF263 in HEB cells and six primary patient-derived glioma cells and discovered an inverse relationship between ZNF263 and SIX3." (PMID 32051553, 2020).
leukemia (1 paper, 2014). A malignant (clonal) hematologic disorder, involving hematopoietic stem cells and characterized by the presence of primitive or atypical myeloid or lymphoid cells in the bone marrow and the blood. "In addition we also studied two non-related transcription factors c-Fos (18211 regions) and ZNF263 (4426 regions) in the K562 (erythromyeloblastoid leukemia) cell line." (PMID 24533055, 2014).
liver cancer (1 paper, 2022). An epithelial or non-epithelial malignant neoplasm that arises from the liver. "Previous research in our group has shown that ZNF263 is overexpressed in liver cancer and promotes the occurrence and development of HCC." (PMID 35896520, 2022).
cancer (8 papers, 2016 to 2025). A tumor composed of atypical neoplastic, often pleomorphic cells that invade other tissues. "We found evidence that for 25 tapRNAs the mutation of CTCF (19 tapRNAs) or ZNF263 (7 tapRNAs) coincides with a significant change in tapRNA expression in the equivalent cancer." (PMID 29540241, 2018). "In addition, we identify a second zinc finger protein (ZNF263) enriched in the conserved sequences of tapRNAs, which is also mutated in cancer cells." (PMID 29540241, 2018). "Indeed, we observed an even more marked enrichment for mutations in ZNF263 sites in cancers than CTCF (p value = 7.58 × 10−14)." (PMID 29540241, 2018). "This raises the possibility that, in addition to CTCF binding sites, mutations in ZNF263 and other motifs associated with tapRNAs may be involved in cancer." (PMID 29540241, 2018). "The ZNF263 is a member of zinc finger proteins containing a C2H2 zinc finger domain and a KRAB repression domain which is associated with basic cellular processes, including development, differentiation, metabolism, apoptosis, and cancer." (PMID 32316525, 2020). "Our analysis highlights the possibility that ZNF263 and potentially other zinc finger factors may play a role in genomic organization, regulating genes that have critical roles in cancer." (PMID 29540241, 2018). "Similarly, seven genes (SGCZ, KANK1, KDM4C, KCNMA1, ZNF263, CDH4, NCAM2) contain partial CNV duplications in both BD‐cancer and BD‐only patients, but the deleted loci are different." (PMID 39140252, 2025). "Intriguingly, two TFBS motifs (ZNF263 and NRF1) had significantly increased relative PWM-scores in cancer compared to 1KG, suggesting binding is enhanced in cancers, and raising the possibility of adaptive evolution at these particular classes of binding sites in cancer." (PMID 27490693, 2016). "Indeed, to our knowledge, no studies have reported the role of ZNF263 in cancer initiation and progression, its correlation with cancer-related events, and the exact regulatory genes." (PMID 35494064, 2022).
tumor (4 papers, 2020 to 2025). "On the other hand, ATF3, BHLHE40, ZNF263, and FOXP2 transcription factors were strongly associated with GADD45B-low tumor cells." (PMID 37608794, 2023). "Various key regulators (CALR, MSI2-Numb, ZNF263/ZNF31, and GINS2) play significant roles in promoting EMT following genomic alterations under different tumor microenvironment conditions." (PMID 39781447, 2025).
ZNF263 also shares sentences with these, for which no sentence is quoted: asthma (2 papers); colon cancer (2); schizophrenia (2); cholangiocarcinoma (1); diabetes (1); dilated cardiomyopathies (1); gastric adenocarcinoma (1); gastric cancer (1); ischemic cardiomyopathies (1); lung carcinoma (1); polycystic kidney and (1).